ADGRL4 (adhesion G protein-coupled receptor L4)
Description:
Endothelial orphan receptor that acts as a key regulator of angiogenesis.
Synonyms: ELTD1; ETL; KPG_003
Tractability: Antibody: UniProt places it where antibodies can reach, with high confidence; UniProt predicts a signal peptide or a membrane-spanning region; its Gene Ontology location is reachable by antibodies, with medium confidence.
Target class: Family B G protein-coupled receptor; Membrane receptor
Gene: Protein-coding gene on chromosome 1 (78,889,764 to 79,282,124, reverse strand). Ensembl gene ENSG00000162618.
Subcellular location: Cell membrane
Gene Ontology:
Molecular function: G protein-coupled receptor activity; calcium ion binding; transmembrane signaling receptor activity
Biological process: G protein-coupled receptor signaling pathway; cell surface receptor signaling pathway
Cellular component: plasma membrane; cytoplasmic vesicle; membrane
Genetic constraint (gnomAD): Loss-of-function variants: 69 observed, 58.53 expected, observed/expected ratio (o/e) 1.18, 90% interval 0.97 to 1.44. The upper end of that interval is the gene's LOEUF score, 1.44, which puts it in group 5 of 6, group 1 being the genes least tolerant of losing a copy. Missense variants: 782 observed, 743.35 expected, observed/expected ratio (o/e) 1.05, 90% interval 0.99 to 1.12. Synonymous variants: 281 observed, 257.5 expected, observed/expected ratio (o/e) 1.09, 90% interval 0.99 to 1.21.
Homologues: Orthologues: chimpanzee ADGRL4 (99% identical), macaque ADGRL4 (97% identical), rabbit ADGRL4 (90% identical), pig ADGRL4 (90% identical), dog ADGRL4 (87% identical), guinea pig ADGRL4 (86% identical), mouse Adgrl4 (79% identical), rat Adgrl4 (73% identical), tropical clawed frog adgrl4 (65% identical), zebrafish adgrl4 (53% identical). Paralogues in human: ADGRL3 (38% identical), ADGRL2 (37% identical), ADGRL1 (35% identical), ADGRE2 (27% identical), ADGRE3 (26% identical), ADGRE5 (26% identical), ADGRE1 (25% identical), ADGRD1 (24% identical), ADGRB2 (21% identical), ADGRB1 (21% identical), ADGRF1 (19% identical), ADGRF5 (19% identical), and 30 more.
Diseases named in the same sentence as ADGRL4 in open-access papers:
ADGRL4 is named in the same sentence as 61 diseases in open-access papers, as found by Europe PMC text mining. Sharing a sentence is not in itself a finding about the gene and the disease. The quoted sentences say what the papers report.
glioblastoma (8 papers, 2018 to 2025). The most malignant astrocytic tumor (WHO grade IV). "A central motivation for this work lies in the frequent observation of overexpressed ADGRL4 in high-grade unresectable tumours such as glioblastoma, which carry limited therapeutic options and dismal survival rates." (PMID 41469374, 2025). "Inhibiting ADGRL4 is a potential therapeutic treatment for currently intractable cancers such as glioblastoma." (PMID 41469374, 2025). "In glioblastoma tumour cells, ADGRL4/ELTD1 silencing led to improved survival." (PMID 33893326, 2021). "In these experiments, ADGRL4 overexpression in a glioblastoma cell line activated JAK/STAT3 signalling, whereas ADGRL4 knockdown attenuated it23." (PMID 41469374, 2025). "We did not observe any downstream signalling events in HEK293T, COS-7 or HUVEC cells, indicating that the interaction between ADGRL4/ELTD1 and the JAK/STAT3/HIF-1α pathway is specific for glioblastoma or other cancer cell types and does not apply within endothelial cells." (PMID 33893326, 2021). "ADGRL4/ELTD1 is not expressed by the majority of cancer cell lines, however it is highly upregulated in some glioblastoma tumour cells and has been shown to be important for glioblastoma cell survival, although the mechanism remains unclear." (PMID 31299890, 2019).
ovarian carcinoma (7 papers, 2016 to 2025). A malignant neoplasm originating from the surface ovarian epithelium. "Systemic vascular ADGRL4/ELTD1 silencing in mice implanted with human tumour xenografts (colorectal and ovarian cancers) decreased microvascular density and induced tumour shrinkage with increased survival without a detrimental systemic vascular effect." (PMID 33893326, 2021). "ADGRL4/ELTD1 is expressed within endothelial cells and vascular smooth muscle cells and is upregulated within tumour-associated endothelial cells across a range of tumour types (head and neck, renal, colorectal, and ovarian cancer)." (PMID 31775252, 2019).
renal carcinoma (4 papers, 2018 to 2025). A carcinoma arising from the epithelium of the renal parenchyma or the renal pelvis. "As detailed below, our literature search identified publications describing five aGPCRs correlated with kidney disease including renal cancer: Adgrb1, Adgrg2 (Gpr64), Adgrl4, Adgrg3, and Adgrf5." (PMID 29468160, 2018). "A possible role of ADGRL4 in renal cancer has been proposed by Masiero and collaborators." (PMID 29468160, 2018).
colorectal tumour (2 papers, 2019 to 2021). "Additionally, Adgrl4/Eltd1 silencing in ovarian and colorectal tumour xenografts in mice was found to substantially limit tumour growth by suppressing tumour-vessel angiogenesis." (PMID 31299890, 2019).
gastric cancer (2 papers, 2023 to 2025). A primary or metastatic malignant neoplasm involving the stomach. "Similarly, ADGRL4 overexpression in a gastric cancer cell line induced MAPK/ERK, whilst knockdown suppressed activation." (PMID 41469374, 2025).
ovarian tumor (2 papers, 2019 to 2021). "In mice, systemic ADGRL4/ELTD1 silencing causes a reduction in size of colorectal and ovarian tumour xenografts (without toxicity) and improves survival." (PMID 31775252, 2019).
Rb (2 papers, 2021). "We focused our investigation on two of these adhesion-GPCRs in Rb tumors, the epidermal growth factor, latrophilin and seven transmembrane domain containing 1 (ELTD1/ADGRL4) and the G-protein receptor 125 (GPR125/ADRGRA3)." (PMID 33430814, 2021).
Anxiety (1 paper, 2019). Intense feelings of nervousness, tension, or panic often arise in response to interpersonal stresses. "Our early experimentation suggests that ADGRL4 agonism might hold utility in the management of acute anxiety." (PMID 31819040, 2019).
diabetic nephropathy (1 paper, 2018). "Increased expression levels were found for ADGRL2, ADGRL4, ADGRE1, ADGRE5, ADGRG2, and ADGRG6 in lupus nephritis and diabetic nephropathy, whereby ADGRL2, ADGRL4 and ADGRE5 were also upregulated in IgA nephropathy." (PMID 29468160, 2018).
IgA nephropathy (1 paper, 2018). "Besides a role in kidney, ADGRL4 upregulation is according to the Neprhoseq database associated with IgA nephropathy (33 human samples, 2.757 fold change, p = 5.18E-12) as well as lupus nephritis (46 human samples, 5.493 fold change, p = 2.46E-7)." (PMID 29468160, 2018).
neuroblastoma (1 paper, 2025). Neuroblastoma (NB) is the most common solid, extracranial childhood tumor. "Finally, silencing ADGRL4 in a neuroblastoma cell line inhibited ERK/STAT3 signalling." (PMID 41469374, 2025).
tumor (21 papers, 2016 to 2025). "ADGRL4 is upregulated in the tumour microenvironment and is implicated in tumour pathogenesis across a broad range of malignancies." (PMID 41469374, 2025). "In general, higher ADGRL4 expression within the tumour microenvironment across the majority of these tumours correlates with more aggressive disease in vitro and in vivo." (PMID 41469374, 2025). "Resolving ADGRL4’s activation mechanism and mapping its precise mode of signalling has broad implications for understanding its role in tumour biology and for designing targeted antagonists." (PMID 41469374, 2025). "In metastatic renal cell cancer, patients with high ADGRL4/ELTD1 expression in the tumor vasculature respond better to sunitinib treatment." (PMID 38287102, 2024). "Overall, our results further supported that ADGRL4+ renal tubule cells were the major cell type in influencing the prognosis of ccRCC and promoting tumor development." (PMID 38287102, 2024). "This is biologically relevant to disease pathology as ADGRL4/ELTD1 is upregulated in endothelial cells found in the tumour microenvironment." (PMID 33893326, 2021). "ADGRL4/ELTD1 is an orphan adhesion GPCR (aGPCR) expressed in endothelial cells that regulates tumour angiogenesis." (PMID 33893326, 2021). "Adhesion G Protein-Coupled Receptor L4 (ADGRL4/ELTD1) is an endothelial cell adhesion G protein-coupled receptor (aGPCR) which regulates physiological and tumour angiogenesis, providing an attractive target for anti-cancer therapeutics." (PMID 31775252, 2019). "The structure is consistent with ADGRL4 being activated by its tethered agonist and represents an important step towards the development of potential inhibitors for the treatment of multiple tumour types." (PMID 41469374, 2025). "ADGRL4/ELTD1 affecting tumor angiogenesis has been reported by several studies." (PMID 38287102, 2024). "While we could not identify the signalling cascades utilised by ADGRL4/ELTD1, we identified several genes whose expression is altered on ADGRL4/ELTD1 overexpression providing possible mechanistic insights into how it may drive tumour angiogenesis." (PMID 33893326, 2021). "This may be due to higher ADGRL4/ELTD1 expression correlating with higher microvessel density and vessel maturity, which thus allows for better systemic anti-cancer drug delivery to the tumour." (PMID 31299890, 2019). "ADGRL4/ELTD1 upregulation in the tumour vasculature has been identified as a common finding in several different cancer types, where it has been hypothesised to promote tumour angiogenesis." (PMID 33893326, 2021). "ADGRL4/ELTD1 is an orphan adhesion G protein-coupled receptor (GPCR) of clinical and therapeutic interest due to its regulation of physiological and tumour angiogenesis." (PMID 31775252, 2019). "Our laboratories have previously identified ADGRL4/ELTD1 as a novel regulator of physiological and tumour angiogenesis." (PMID 31299890, 2019). "The further study of such markers related to ADGRL4/ELTD1 function will also provide valuable information for monitoring the efficacy of future therapies aiming to inhibit the expression and/or function of ADGRL4/ELTD1 in the tumour microenvironment." (PMID 33893326, 2021). "New insights into ADGRL4/ELTD1′s function within endothelial biology, and new experimental targets within the endothelial tumour microenvironment are clinically relevant findings that could be investigated as a means to better treat cancer." (PMID 31775252, 2019). "Furthermore, we found that ETS1- and ELK3-interacting target genes were all up-regulated in ADGRL4+ renal tubule cells, and none of them were expressed in para-tumor-derived renal tubule cells." (PMID 38287102, 2024).
cancer (14 papers, 2015 to 2025). A tumor composed of atypical neoplastic, often pleomorphic cells that invade other tissues. "ADGRL4 is a cancer-implicated adhesion GPCR whose ability to couple to G proteins had been unclear." (PMID 41469374, 2025). "This indicated that ADGRL4+ renal tubule cells were an essential cancer cell subcluster in ccRCC, and might be the main causative factor for aggregation or generation among other cell subclusters." (PMID 38287102, 2024). "Here, we present evidence for the direct coupling of a G protein to ADGRL4 and describe the high-resolution cryo-EM structure of its active-state conformation, offering mechanistic insights into how an aGPCR implicated in multiple cancers is activated and how it could be pharmacologically targeted." (PMID 41469374, 2025). "Our laboratory identified ADGRL4/ELTD1, an orphan GPCR belonging to the adhesion GPCR (aGPCR) family, as a novel regulator of angiogenesis and a potential anti-cancer therapeutic target." (PMID 31299890, 2019). "ADGRL4/ELTD1 is not expressed by the majority of cancer cell lines." (PMID 31775252, 2019).
infection (2 papers, 2022 to 2024). The state of being infected such as from the introduction of a foreign agent such as serum, vaccine, antigenic substance or organism. "A comprehensive analysis of the brain transcriptomic profile in response to infection with different SARS-CoV-2 variants found that ADGRL4/ELTD1 was one of five downregulated genes common to all variants." (PMID 38674024, 2024). "In response to infection with different SARS-CoV-2 variants, ADGRL4/ELTD1 was one of five downregulated genes in the brain transcriptomic profile and common to all SARS-CoV-2 variants." (PMID 38674024, 2024).
ADGRL4 also shares sentences with these, for which no sentence is quoted: glioma (12 papers); cardiac hypertrophy (7); colorectal cancer (6); breast carcinoma (5); hepatocellular carcinoma (3); brain cancer (2); depression (2); thrombotic microangiopathies (2); atherosclerosis (1); brain glioma (1); breast tumours (1); cardiac diseases (1); clear cell renal cell carcinoma (1); colitis (1); congenital heart defects (1); Constipation (1); endometriosis (1); endothelial dysfunction (1); experimental autoimmune encephalomyelitis (1); fibrosis (1); glomerulopathy (1); head and neck squamous cell carcinoma (1); heart (1); heart failure (1); hypertrophy (1); kidney failure (1); lentivirus infection (1); liver cancer (1); lupus nephritis (1); lymph node metastasis (1).
A further 17 diseases each share a sentence with ADGRL4 in 1 paper.